ALG3 (ALG3 alpha-1,3- mannosyltransferase)
Description:
Dol-P-Man:Man(5)GlcNAc(2)-PP-Dol alpha-1,3-mannosyltransferase that operates in the biosynthetic pathway of dolichol-linked oligosaccharides, the glycan precursors employed in protein asparagine (N)-glycosylation. The assembly of dolichol-linked oligosaccharides begins on the cytosolic side of the endoplasmic reticulum membrane and finishes in its lumen. The sequential addition of sugars to dolichol pyrophosphate produces dolichol-linked oligosaccharides containing fourteen sugars, including two GlcNAcs, nine mannoses and three glucoses. Once assembled, the oligosaccharide is transferred from the lipid to nascent proteins by oligosaccharyltransferases. In the lumen of the endoplasmic reticulum, adds the first dolichyl beta-D-mannosyl phosphate derived mannose in an alpha-1,3 linkage to Man(5)GlcNAc(2)-PP-dolichol to produce Man(6)GlcNAc(2)-PP-dolichol. Man(6)GlcNAc(2)-PP-dolichol is a substrate for ALG9, the following enzyme in the biosynthetic pathway.
Synonyms: NOT; NOT56L; Not56; CDGS4; D16Ertd36e; CDG1D; CDGS6
Tractability: Antibody: UniProt predicts a signal peptide or a membrane-spanning region. PROTAC: ubiquitination databases record sites on it; its protein half-life has been measured.
Target class: Enzyme; Transferase
Gene: Protein-coding gene on chromosome 3 (184,242,301 to 184,249,548, reverse strand). Ensembl gene ENSG00000214160.
Subcellular location: Endoplasmic reticulum membrane
Pathways (Reactome):
Disease: Defective ALG3 causes CDG-1d
Metabolism of proteins: Biosynthesis of the N-glycan precursor (dolichol lipid-linked oligosaccharide, LLO) and transfer to a nascent protein
Gene Ontology:
Molecular function: dol-P-Man:Man(5)GlcNAc(2)-PP-Dol alpha-1,3-mannosyltransferase activity; protein binding; alpha-1,3-mannosyltransferase activity; mannosyltransferase activity
Biological process: dolichol-linked oligosaccharide biosynthetic process; protein N-linked glycosylation
Cellular component: endoplasmic reticulum membrane; lumenal side of endoplasmic reticulum membrane
Genetic constraint (gnomAD): Loss-of-function variants: 39 observed, 52.38 expected, observed/expected ratio (o/e) 0.74, 90% interval 0.57 to 0.97. The upper end of that interval is the gene's LOEUF score, 0.97, which puts it in group 4 of 6, group 1 being the genes least tolerant of losing a copy. Missense variants: 520 observed, 569.51 expected, observed/expected ratio (o/e) 0.91, 90% interval 0.85 to 0.98. Synonymous variants: 252 observed, 249.16 expected, observed/expected ratio (o/e) 1.01, 90% interval 0.91 to 1.12.
Gene-disease validity (ClinGen):
ClinGen rates the evidence that ALG3 causes each of these diseases.
ALG3-congenital disorder of glycosylation (autosomal recessive): Definitive. A form of congenital disorders of N-linked glycosylation characterized by severe neurological involvement, including hypotonia, developmental delay, intellectual disability, postnatal microcephaly, and progressive brain and cerebellar atrophy.
Homologues: Orthologues: chimpanzee ALG3 (99% identical), macaque ALG3 (97% identical), pig ALG3 (94% identical), dog ALG3 (94% identical), guinea pig ALG3 (92% identical), mouse Alg3 (89% identical), rabbit ALG3 (71% identical), rat Alg3 (70% identical), tropical clawed frog alg3 (66% identical), zebrafish alg3 (65% identical), Drosophila melanogaster Alg3 (49% identical), Caenorhabditis elegans algn-3 (44% identical).
Diseases named in the same sentence as ALG3 in open-access papers:
ALG3 is named in the same sentence as 56 diseases in open-access papers, as found by Europe PMC text mining. Sharing a sentence is not in itself a finding about the gene and the disease. The quoted sentences say what the papers report.
breast carcinoma (18 papers, 2014 to 2025). "In humans, ALG3 gene amplification, associated with poor outcomes in breast cancer, has also been observed in various other human cancers." (PMID 40789468, 2025). "The findings recorded from the univariate analysis highlighted that T, N, M stage and ALG3 expression levels were substantially linked to OS rate in breast cancer patients." (PMID 38329424, 2024). "To gain insights into the association of ALG3 expression level and significant pathways, we performed spatially resolved transcriptomics on breast cancer samples." (PMID 38329424, 2024). "ALG3 was also found to promote the proliferation and metastasis of breast cancer cells, and overexpression of ALG3 was associated with poor prognosis." (PMID 35774357, 2022). "The association of ALG3 with prognosis of breast cancer patients was confirmed by immunohistochemistry." (PMID 33931075, 2021). "Although previous studies have implicated that ALG3 was involved in breast cancer progression, whether ALG3 functioned as an onco-immunological biomarker in breast cancer was still unknown." (PMID 38329424, 2024). "In addition, we validated the biological function and explored the underlying mechanisms of ALG3 in breast cancer." (PMID 38329424, 2024). "ALG3 has been found to be abnormally expressed in several cancers, including bladder, ovarian, and breast cancers." (PMID 40475760, 2025). "CRISPR-Cas9 depletion of ALG3 reduced the staining pattern of all three lectins, indicating that ALG3 is functionally required for protein glycosylation using α-1,3 mannose in breast cancer cells with hyperactive PI3K signaling." (PMID 40789468, 2025). "In summary, we made comprehensive analysis of ALG3 in pan-cancer and validation of ALG3 as an onco-immunological biomarker in breast cancer." (PMID 38329424, 2024). "In breast cancer patients who had pathology complete response, elevated expression levels of ALG3 were resistant to the chemotherapeutics." (PMID 38329424, 2024). "An elevated level of ALG3 expression in breast cancer patients is predictive of a dismal prognosis because it stimulates the proliferative and metastatic capacities of cancer cells." (PMID 38329424, 2024). "After that, we focused on breast cancer in an effort to gain a greater comprehension of ALG3-elicited intercellular interactions as well as the activation of signal transduction pathways." (PMID 38329424, 2024). "The elevated expression level of ALG3 was found in breast cancer, especially in HER-2 positive and triple negative breast cancer, as revealed by the UALCA database." (PMID 38329424, 2024). "ALG3 inhibition decreased breast cancer cell growth ability, as revealed by MTT and colony formation assays." (PMID 38329424, 2024). "The median value of ALG3 was used as the threshold to classify patients with breast cancer into high- and low-expression groups." (PMID 38329424, 2024). "We investigated the potential role of ALG3 as a predictive factor in breast cancer patients based on data derived from the TCGA database." (PMID 38329424, 2024). "Subsequently, the time receiver operating characteristic (ROC) analysis was carried out to compare the prediction power and risk score of ALG3 for OS and DFS in breast cancer." (PMID 38329424, 2024). "With the use of the CCLE database, we revealed the elevation of ALG3 expression in most kinds of breast cancer cell lines." (PMID 38329424, 2024). "Some studies have shown that the overexpression of ALG3 is related to lymph node metastasis in esophageal squamous cell carcinoma and promotes stem cell property and radiation resistance in breast cancer by regulating the glycosylation of TGF-β receptor II." (PMID 36575396, 2022).
breast carcinoma (continued). "In a 30-sample breast cancer cohort (including 15 radioresistant and 15 radiosensitive tumors), ALG3 was the most highly expressed of the ALG family in the radiation-resistant tissue." (PMID 35899200, 2022). "ALG3 can increase the radioresistance and tumor stemness of breast cancer cells and can upregulate several key CSC-like markers (Nanog, OCT4, and SOX2) by promoting the glycosylation of TGF-beta receptor II." (PMID 35899200, 2022). "Studies have demonstrated that ALG3 is overexpressed in oral squamous cell carcinoma, non–small cell lung cancer, and breast cancer and contributes to drug resistance in the acute myeloid leukemia." (PMID 35782861, 2022). "Gain and loss of function experiments demonstrated that upregulating ALG3 promoted, while silencing ALG3 improved resistance of breast cancer cells to radiation therapy in vitro and in vivo." (PMID 33931075, 2021). "For breast cancer patients with low ALG3 levels, radiation therapy is beneficial to improve prognosis as a therapeutic strategy." (PMID 33931075, 2021). "We further used orthotopic xenograft tumor models to determine the role of silencing ALG3 in sensitivity of breast cancer cells to radiation in vivo." (PMID 33931075, 2021). "Then, we further analyzed the clinical significance of ALG3 in LRFS in breast cancer patients based on radiotherapy treatment history." (PMID 33931075, 2021). "Next, orthotopic xenograft tumor model was used to investigate the effect of ALG3 overexpression on response of breast cancer cells to radiation in vivo." (PMID 33931075, 2021). "In this study, we found that ALG3 was dramatically upregulated in radioresistance breast cancer tissues, which predicted a high rate of recurrence as well as poor mortality in breast cancer patients." (PMID 33931075, 2021). "Collectively, downregulation of ALG3 sensitized breast cancer cells to radiation in vitro and in vitro." (PMID 33931075, 2021). "Further assessment of ALG3 modulation of CSCs in breast cancer demonstrated that ALG3-overexpressing cell lines also demonstrated increased NANOG, OCT4, and SOX2 expression (CSC associated genes) and increased tumorsphere formation capabilities." (PMID 34680503, 2021). "Then, Univariate and Multivariate analysis were performed to assess the independent predictive ability of ALG3 in breast cancer patients." (PMID 33931075, 2021). "ALG3 expression was dramatically upregulated in radioresistant human-breast cancer tissue compared with radiosensitive breast cancer tissues." (PMID 33931075, 2021). "ALG3 was the most significantly overexpressing gene among ALG family in radioresistant breast cancer tissue." (PMID 33931075, 2021). "Collectively, our results indicate that overexpression of ALG3 is correlated with poor survival in breast cancer patients." (PMID 33931075, 2021). "For patients with low ALG3 levels, radiation remains an effective mainstay therapy to prevent early recurrence in breast cancer." (PMID 33931075, 2021). "The therapeutic efficacy of radiation in breast cancer patients was further investigated based on the ALG3 expression levels, and the results showed that radiation therapy significantly improved LRFS in breast cancer patients with low ALG3 levels." (PMID 33931075, 2021). "Together, our study demonstrated that ALG3 overexpression contributed to the radioresistance of breast cancer though regulating glycosylation of TGF-β receptor II." (PMID 33931075, 2021). "Expression levels of ALG1, ALG2, ALG3, ALG8, ALG9, ALG12 and ALG13 were differentially upregulated in radioresistant breast cancer tissues compared with those in radiosensitive tissues, particularly ALG3 with the highest level (4.53-fold change)." (PMID 33931075, 2021). "Similarly, depletion of ALG3 also significantly reduced cell proliferation in PTEN-deficient, AKT-hyperactivated MDA-MB-468 breast cancer cells." (PMID 40789468, 2025). "Studies have also indicated that ALG3 expression is correlated with poor outcomes in breast cancer." (PMID 40789468, 2025).
breast carcinoma (continued). "The biological function and the fundamental processes of ALG3 in breast cancer were investigated." (PMID 38329424, 2024). "The biological effects of ALG3 were verified by breast cancer cells." (PMID 38329424, 2024). "ALG3 might be a viable treatment target for cancer therapy, particularly in the case of breast cancer." (PMID 38329424, 2024). "The inhibition of ALG3 activity resulted in a decrease in the growth rate of breast cancer cells." (PMID 38329424, 2024). "In the OS analysis, ALG3 expression level could anticipate the breast cancer patients’ prognoses over 1, 3, and 5 years, and its AUC values were 0.612, 0.629, and 0.606, correspondingly." (PMID 38329424, 2024). "Furthermore, we focused on breast cancer to examine the influence of ALG3-mediated signaling pathways and intercellular interactions in the advancement of tumors." (PMID 38329424, 2024). "Finally, the multivariate and univariate Cox regression analyses were executed to establish the prognostic relevance of ALG3 in breast cancer." (PMID 38329424, 2024). "We further performed a functional assay to explore ALG3’s function in breast cancer cells." (PMID 38329424, 2024). "In addition, we revealed that ALG3 expression was elevated in breast cancer samples by utilizing Human Protein Atlas (HPA) database." (PMID 38329424, 2024). "Breast cancer patients exhibiting subtypes C1, C2, C4, and C6 were shown to have elevated expression levels of ALG3, suggesting that ALG3 may have a role in promoting the growth of tumors." (PMID 38329424, 2024). "ALG3 has been reported to be overexpressed in cervical and radioresistant breast cancer cells." (PMID 36231102, 2022). "Finally, the clinical correlation between ALG3 expression and prognosis of breast cancer patients was further analyzed in 376 paraffin-embedded breast cancer tissues using IHC staining." (PMID 33931075, 2021). "Moreover, HSF2 mediates expression of the ALG3 enzyme, which subsequently promotes the growth and migration of breast cancer cells." (PMID 35087869, 2021). "Collectively, these results demonstrate that ALG3 promotes CSC-like traits in breast cancer." (PMID 33931075, 2021). "Importantly, average expression levels of ALG3 in radioresistant breast cancer cell lines were significantly higher than those in radiosensitive breast cancer cell lines." (PMID 33931075, 2021). "Finally, our findings showed that radiation played an important role in preventing early recurrence in breast cancer patients with low ALG3 levels, but it had limited efficacy in ALG3-overexpressing breast cancer patients." (PMID 33931075, 2021). "By contrast, silencing ALG3 dramatically suppressed cancer stemness in breast cancer cells." (PMID 33931075, 2021). "Our findings further suggested that ALG3 may serve as an effective target in breast cancer patients with high ALG3 levels." (PMID 33931075, 2021). "ALG3 expression was further analyzed in 15 radioresistant patients and 15 radiosensitive breast cancer tissues using Western blot, and the results showed ALG3 expression was dramatically increased in the radioresistant group compared to that in the radiosensitive group." (PMID 33931075, 2021). "Therefore, our findings provide convincing evidence that ALG3 serves as a promising target to enhance sensitivity of breast cancer to radiotherapy." (PMID 33931075, 2021). "Importantly, both glycosylation blocker, tunicamycin, and TGFBR2 inhibitor, LY2109761, reduced cancer stemness and radioresistance in ALG3-overexpressing breast cancer cells." (PMID 33931075, 2021). "However, the clinical significance and functional role of ALG3 in radioresistance of breast cancer need to be further elucidated." (PMID 33931075, 2021). "Collectively, our results suggest that amplification or gain-induced ALG3 overexpression may play a crucial role in radioresistance of breast cancer." (PMID 33931075, 2021).
breast carcinoma (continued). "As the CD44+CD24− subpopulation is considered to exhibited cancer stem-like traits in breast cancer, we further investigated whether ALG3 affects the percentage of CD44+CD24−breast cancer cells." (PMID 33931075, 2021). "Collectively, our results indicate that ALG3 may serve as a potential marker to predict radiosensitivity, as well as a radiation sensitizer to improve radioresistance in breast cancer patients with high ALG3 levels." (PMID 33931075, 2021). "Conversely, silencing ALG3 increased the radiosensitivity and repressed cancer stemness in vitro, and more importantly inhibition of ALG3 effectively increased the radiosensitivity of breast cancer cells in vivo." (PMID 33931075, 2021). "Another signature gene, ALG3, has a higher expression in samples of breast cancer with advanced stages than those with early stages and the decreased expression of PSD4 (EFA6B) was associated with poor prognosis of patients with breast cancer." (PMID 31355144, 2019). "In vitro, knockdown of ALG3 could decrease the proliferation of breast cancer cells." (PMID 38329424, 2024). "Furthermore, we used GSE152048 to examine the ALG3 expression in diverse cells of breast cancer." (PMID 38329424, 2024). "Thus, the critical findings of this current study present novel insights into the molecular mechanisms by which ALG3 promotes the resistance of breast cancer cells to radiation therapy, which will facilitate to improve radioresistance of breast cancer by targeting ALG3." (PMID 33931075, 2021). "However, the biological role of ALG3-induced glycosylation in radioresistant breast cancer remains largely unknown." (PMID 33931075, 2021). "A single-cell transcriptome sequencing investigation illustrated that ALG3 expression was substantially related to hypoxia, metastasis, invasion, EMT, apoptosis, quiescence, and DNA repair in breast cancer." (PMID 38329424, 2024). "According to previous studies, ALG3 promotes the invasion, migration, and proliferation of oral squamous cell carcinoma, non-small cell lung cancer, and breast cancer, but the expression of ALG3 and its relation with the prognosis of HCC patients remains unknown." (PMID 35782861, 2022). "In summary, our results demonstrate that ALG3 overexpression promotes glycosylation of TGFBR2 and activates TGF-β signaling, which further promotes radioresistance and CSC-like traits in breast cancer." (PMID 33931075, 2021). "Therefore, we further investigated whether ALG3 could promote breast cancer stem-like traits." (PMID 33931075, 2021). "Overexpression of ALG3 predicted poor clinicopathological characteristics and overall survival (OS), and early local recurrence-free survival (LRFS) in breast cancer patients." (PMID 33931075, 2021). "Collectively, our results indicate that ALG3 promotes radioresistance and CSC-like traits by activating TGF-β signaling dependent on glycosylation of TGFBR2 in breast cancer." (PMID 33931075, 2021). "Downregulation of ALG3 reduced, while upregulation of ALG3 increased NANOG, OCT4 and SOX2 expression in breast cancer cells under radiation treatment." (PMID 33931075, 2021). "In breast cancer cells, HSF2 regulates ALG3 enzyme expression to enhance cell proliferation and migration." (PMID 34917120, 2021). "Core metabolic prognostic signatures are identified, comprising NUDT1 and GAPDH in kidney renal cell carcinoma and SQLE, ALG3 and PSPH in two independent breast carcinoma cohorts." (PMID 27358048, 2016). "CRISPR-Cas9 depletion of ALG3 (sgALG3_2 and sgALG3_3) led to induction of ER stress in MDA-MB-468 breast cancer cells, as determined by increased protein and mRNA of the ER stress and UPR marker 78 kDA glucose-regulated protein/binding immunoglobulin protein (GRP78/BiP)." (PMID 40789468, 2025).